NOD2 (nucleotide binding oligomerization domain containing 2)
Diseases named in the same sentence as NOD2 in open-access papers (continued):
Sharing a sentence is not in itself a finding about the gene and the disease.
Obesity (continued). "Moreover, resveratrol and curcumin might inhibit obesity-related metainflammatory signals driven by toll-like receptor 4 (TLR4) and nucleotide-binding oligomerization domain 2 (NOD2)." (PMID 30134638, 2018). "We also clearly show that a deletion of NOD2 within hematopoietic cells, an immune cell precursor population usually considered a key regulator of inflammation during diet-induced obesity, is not involved as primary mechanism for the control of glucose metabolism in response to a fat-enriched diet." (PMID 25666722, 2015). "Our results showing abrogation of obesity and metabolic changes in Nod2−/− HFD mice by antibiotics and transfer of increased sensitivity to obesity in germ-free mice by microbiota from Nod2−/− HFD mice suggest that Nod2 may protect mice from harboring such “obese microbiota”." (PMID 28373658, 2017). "Thus, Nod2 differentially regulates the response of BALB/c and C57BL/6 mice to HFD, which emphasizes the importance of the host’s entire genetic background in regulation of obesity and metabolic syndrome and reflects the variability in the development of disease in humans." (PMID 28373658, 2017). "However, we hypothesize that obesity‐induced modifications, combined with the absence of NOD1 itself, may lead to compensatory activation of alternative PRRs, as suggested by the increased pulmonary expression of Nod2 observed in NOD1‐deficient mice." (PMID 40616268, 2025). "Therefore, the deletion of NOD2, but not NOD1, increased inflammation in the lung parenchyma during obesity." (PMID 39507249, 2024). "Hence, we originally hypothesized that lacking NOD2 detection of this type of PGN (i.e., MDP) would improve insulin sensitivity during obesity." (PMID 25666722, 2015).
Arthritis (31 papers, 2008 to 2025). Inflammation of a joint. "Both individuals with known NOD2 pathogenic variants developed a classical BS triad (granulomatous recurrent uveitis, dermatitis and arthritis)." (PMID 38927735, 2024). "A search for NOD2 gene mutation should be considered if a typical triad of arthritis, rash, uveitis is present." (PMID 37721575, 2023). "Here, we present a case study of a patient with a history of rash, arthritis and binocular uveitis, whose genetic testing revealed a heterozygous mutation in the NOD2 gene, leading to a BS diagnosis." (PMID 37386644, 2023). "We determined the effects of Nod2 deficiency on B. burgdorferi-induced arthritis and inflammation by characterizing joint swelling in infected mice using both caliper measurements as well as histological scoring by blinded investigators." (PMID 21387014, 2011). "In a model where arthritis is induced via a single injection of peptidoglycan, Nod2 deficiency results in decreased inflammation." (PMID 21387014, 2011). "A future investigation on the association between NOD2 genotypes and ultrasound-defined severity of arthritis in a larger number of patients may identify the high-risk genotypes for severe synovial inflammation." (PMID 24713464, 2014). "In contrast, in B. burgdorferi-induced arthritis, Nod2 deficiency increases inflammation." (PMID 21387014, 2011). "Thus, it does not appear that loss of bacterial control due to a decrease in defensins is the mechanism by which Nod2 deficient mice have increased B. burgdorferi-induced arthritis." (PMID 21387014, 2011). "We reaffirm the basic definition of YAOS (OMIM Entry #617321) as a syndrome of episodic fever, rash, arthralgia/arthritis, chronic gastrointestinal symptoms, and sicca-like symptoms and describe novel clinical features identified in a sizeable cohort along with a previously unreported NOD2 variant." (PMID 39430755, 2024). "In an arthritis mouse model, intra-articular injection of zymosan induces cathepsin release in a Dectin-1- and NOD2-dependent manner." (PMID 28671985, 2017). "In the cross-regulation between PGRP and NOD, it has been reported that mouse PGLYRP-2 cooperates with NOD2 to activate pro-inflammatory genes in a PGN-induced arthritis model." (PMID 27991595, 2016). "Particularly, the nod2 gene had been described as a positive modulatory element in a model of PG-induced arthritis and autoimmune liver injury." (PMID 25643148, 2015). "In animal models, Nod2 has been shown to be required for the development of acute, peptidoglycan-induced arthritis, and has been shown to contribute to the inflammatory response induced by a number of bacterial pathogens." (PMID 21387014, 2011). "Here we reported a proband harboring a novel C483W mutation in the NOD2 gene with wide spread brownish plaques, symmetric “boggy” arthritis and non-caseating granulomas in the skin specimen suspicious of BS/EOS." (PMID 36192768, 2022). "While there are numerous differences between these models that could explain why Nod2 could play opposite roles, one obvious difference is in the kinetics of arthritis development." (PMID 21387014, 2011). "To test this possibility in a setting free of an endogenous microflora that could be enhancing inflammation in the absence of NOD2 anti-microbial function (as might be the case in the GI tract) we assessed the severity of anti-collagen antibody-induced arthritis in NOD2 KI mice and WT littermates." (PMID 36189261, 2022). "However, we find that in vivo, Nod2 deficient mice demonstrate the opposite phenotype, where loss of Nod2 results in increased rather than decreased arthritis." (PMID 21387014, 2011). "However, B. burgdorferi infection of Nod2 deficient mice resulted in increased rather than decreased arthritis and carditis compared to control mice." (PMID 21387014, 2011).
Arthritis (continued). "NOD2 and PGLYRP-2 showed a synergistic effect in the development of local inflammation in an arthritis mice model since PGLYRP2−/− NOD2−/− mice were resistant to PGN or MDP induced arthritis." (PMID 31416116, 2019). "We have previously reported that in vivo stimulation of NOD2 with MDP induces the emergence of circulating Ly6Clow patrolling monocytes and also that the presence of Ly6Clow monocytes was required for Treg cell recruitment in a serum transfer-induced arthritis mice model." (PMID 29445379, 2018). "In humans, B. burgdorferi-induced IL-1β was partly NOD2-dependent, but the role of this PRR in the development of arthritis has never been demonstrated." (PMID 23148704, 2012).
viral infection (31 papers, 2011 to 2025). "NOD2 is a pattern recognition receptor that recognizes pathogen-associated molecular patterns in the innate immune response and initiates an immune response, thereby reducing the risk of viral infection." (PMID 39493765, 2024). "Thus we observed a selective defect in NOD2-deficient T cell responses only during a live viral infection." (PMID 23405246, 2013). "In this regard, recent literature indicates that frameshift mutations in the NOD2 gene, such as those associated with CD as in our patient, impair the innate immune response to viral infections by disrupting NOD2's regulatory and signaling functions." (PMID 41488909, 2025). "This trait has been confirmed in other viral infections, such as foot-and-mouth disease, to counteract NOD2 to antagonize antiviral activity." (PMID 38668261, 2024). "We recently showed that 25HC activates FAK in macrophages and MEFs following Nod2 activation and virus infection." (PMID 34551004, 2021). "Various stimuli (e.g., virus infection, activation of pattern recognition receptors like Nod2, TLR) induce C25H gene expression leading to production of 25HC." (PMID 34551004, 2021). "Viral infection augments signaling through NOD1/NOD2 pathways to oppose secondary bacterial infection." (PMID 34573406, 2021). "We recently identified α5β1 integrin complex involved in triggering 25HC-mediated pro-inflammatory response during Nod2 activation and virus infection." (PMID 34551004, 2021). "In mandarinfish, both the NOD1 and NOD2 gene were found to be activated in viral infection, mimicked by treatment with the viral analogue Poly I:C, revealing that NODs are sensitive to the protective immune response against viral invasion." (PMID 30119658, 2018). "Whereas RICK is a critical signaling intermediate in the NOD2 pathway following detection of bacterial component, viral infection rather triggered the NOD2-IPS–1 axis to elaborate effective immune response." (PMID 26444420, 2015). "Loss-of-function NOD2 mutations result in defective negative regulation of TLR-mediated proinflammatory and type I interferon responses, which can lead to dysregulated inflammation during viral infections." (PMID 41488909, 2025). "This suggests that NOD2 may help balance the immune response, promoting anti-inflammatory cytokine production to limit immunopathology during viral infections." (PMID 40732729, 2025). "Disruption of NOD2 gene has been associated with impaired resistance to inflammatory diseases, while its interaction with BRSV suggests a potential role in the innate immune response to viral infection." (PMID 41144480, 2025). "In contrast, FMDV 2B or 2C interacts with NOD2 during viral infection." (PMID 39329913, 2024). "Our findings suggest that viral infection is needed to upregulate NOD2 in these cells." (PMID 38668261, 2024). "However, in the NLR family, there are members of great importance for inflammatory functions such as NLRP3 or NLRX1, which regulatory functions on RIG-I/MAVS pathway and are important in viral infection, and NOD2, a less studied effector in viral infections." (PMID 38668261, 2024). "These receptors respond to several viral infections, among them NOD2, a very dynamic NLR, whose role in dengue virus (DENV) infection remains unclear." (PMID 38668261, 2024). "In addition to differences in the recognition and regulation of bacterial infection, NOD1 and NOD2 also display different functions during viral infections." (PMID 35638852, 2022). "Furthermore, NOD2 is involved in the immune response to both bacterial and viral infections, suggesting the possibility to improve the resistance to other diseases by selection of NOD2 alleles." (PMID 34573406, 2021). "Genetic selection of the NOD2-2197C genotype may improve resistance to bacterial and/or viral infection, including PCV2b, contributing to the prevention of growth retardation or death during the rearing period due to an enhanced response to the ligand." (PMID 34573406, 2021).
viral infection (continued). "Based on our study, we propose a “biphasic” model for Nod2 activation during viral infection." (PMID 30931941, 2019). "For example, when the host NOD2/RIG-I signaling is activated via bacterial/viral infection, a feedback regulation might contribute to maintain the homeostasis of immune responses." (PMID 28555019, 2017). "Infection of HFFs and U373 glioma cells with laboratory-adapted strains and a clinical isolate of HCMV resulted in a significant induction of NOD2 as early as 2 h after virus infection, required an intact viral genome and persisted throughout a full replication cycle." (PMID 24671169, 2014). "This hypothesis is consistent with the opposing roles of Nod2 and Atg16L1 downstream of viral infection." (PMID 21994779, 2011). "This was confirmed in vivo, with NOD2 knockout mice demonstrating an increased susceptibility to infection with respiratory syncytial virus or influenza, although increased susceptibility to viral infections has not yet been shown in humans expressing NOD2 polymorphisms." (PMID 29515999, 2018). "In addition, we did not observe any cleavage of the upstream receptors NOD1 and NOD2, nor other crucial signaling proteins implicated in innate immune response to virus infection, including MAVS and STING." (PMID 26297639, 2015). "However, a growing body of evidence suggests that NOD2 triggering could effectively be beneficial against several viral infections including IAV." (PMID 22590599, 2012). "NOD2 extends its influence on the antiviral realm by activating IRF3 and inducing IFN-β production, enhancing the host’s ability to combat viral infections." (PMID 39329913, 2024). "Therefore, the diminished response caused by the NOD2 mutation may result in the failure of protection against secondary infection, despite viral infection augmenting the expression of NOD2 and its signaling receptor RIP2 (receptor-interacting-serine/threonine-protein kinase 2)." (PMID 34573406, 2021). "NOD2 is an essential NLR that participates in the recognition of bacterial invasion and viral infection." (PMID 29872030, 2019). "The nucleotide-binding oligomerization domain 2 (NOD2) receptor is known to recognize ssRNA viruses such as IAV, but its role in the inflammatory process during viral infections remains to be clarified." (PMID 29445379, 2018). "Of them, nucleotide-binding oligomerization 2 (NOD2) and multi-protein inflammasome complex (i.e., NOD-, LRR-and pyrine domain-containing 3 (NLRP3)) are well studied for sensing the viral infections." (PMID 29734779, 2018). "The BIRC2 and BIRC3 genes (which had altered expressions in ASD, asthma, ear infection, and bacterial and viral infections) are members of the inhibitor-of-apoptosis protein family and are key regulators of NOD1 and NOD2 innate immunity signaling." (PMID 27842596, 2016). "NOD2 was reported to induce IFNs production following ssRNA transfection and respiratory syncytial and influenza A virus infection, whereas NLRP3 inflammasome activation was reported in viral infections such as IAV, encephalomyocarditis virus, and HCV." (PMID 29734779, 2018). "NOD2 and its downstream adaptor protein IPS–1 have been found to be essential for LTB4-mediated effects against IAV infection, as absence of NOD2 or IPS–1 diminished its capacity to control viral infection." (PMID 26444420, 2015). "Consistent with the reported requirement for NOD2 but not NOD1 for the IFNβ response following ssRNA virus infection, only a minimal stimulation was observed in 293/hNOD1 cells." (PMID 23936340, 2013). "Therefore, the dual role of NOD2 in monocyte recruitment and type I IFN production deserves closer attention in relationship with the protective action of MDP against viral infection." (PMID 22590599, 2012). "We suggest that as in viral infection, M. ovipneumoniae infection can activate NOD2 but not NOD1." (PMID 32778560, 2020).
viral infection (continued). "Upon entry of the virus by endocytosis in airway epithelial cells, viral infection can be detected through many innate sensors such as Toll-like receptors (TLR), retinoic acid-induced like receptor (RIG-I), melanoma-differentiation gene 5 (MDA5) and Nod-like receptor 2 (NOD2)." (PMID 26381265, 2015). "In the absence of inhibition of NOD2 signaling by RIG-I in RIG-I−/− mice, unrestrained NOD2 might optimize innate immune responses to viral infections and improve survival." (PMID 30532653, 2018).
colorectal cancer (28 papers, 2007 to 2025). A primary or metastatic malignant neoplasm that affects the colon or rectum. "The dysregulation of NOD2, often due to genetic variations (polymorphisms), has been implicated in chronic gut inflammation and, consequently, increased colorectal cancer (CRC) risk." (PMID 40563649, 2025). "Such cytokine is sharply induced by microbiota, in Nod2-dependent and –independent pathways, during weaning for lowering the risk of developing colorectal cancer later in life." (PMID 37415975, 2023). "NOD2 is one of the most studied NLRs in the GI tract because polymorphisms in the gene that encodes NOD2 have been strongly associated with IBDs and colorectal cancer." (PMID 34819919, 2021). "A meta-analysis of 30 studies in Caucasians revealed a higher risk for colorectal cancer in patients with NOD2 SNPs rs2066844, rs2066845 and rs2066847." (PMID 34198814, 2021). "Polymorphisms in Nod2 are also linked to colorectal cancer, and in experimental models, Nod2-deficiency was shown to enhance sensitivity to colorectal cancer with hyperinflammation in the gut22,23." (PMID 33239685, 2020). "So far, no comprehensive meta-analysis has investigated the overall cancer risk in relation to NOD2 polymorphisms, except for a meta-analysis only concerning colorectal cancer in 2010." (PMID 24586700, 2014). "After that, increasing studies focused on the association between NOD2 polymorphisms and risks of various cancers including gastric cancer, colorectal cancer, endometrial cancer, breast cancer, ovarian cancer, laryngeal cancer and so on." (PMID 24586700, 2014). "In the present study, we compared the frequency of a series of polymorphisms in different inflammatory response genes associated with IBD (DLG5, IL-4, OCTN, TNFα and NOD2) in colorectal cancer cases against controls." (PMID 18433468, 2008). "Studies on a larger cohort of colorectal cancer cases and matched controls are necessary to clarify the relationship between the TNFα -1031T/T and NOD2 3020insC polymorphisms and CRC." (PMID 18433468, 2008). "In a previous investigation, we found a significant association between the NOD2 frameshift constitutional mutation (3020insC) and the risk of colorectal cancer in patients diagnosed above the age of 50 years (OR = 2.23; p = 0.0046)." (PMID 18433468, 2008). "For the first time, NOD2 polymorphisms were linked to the risk of colorectal cancer." (PMID 38755492, 2024). "In addition, patients with NOD2 polymorphisms are reportedly at high risk of lymphoma, colorectal cancer, gastric cancer, breast cancer, ovarian cancer, lung cancer, and laryngeal cancer, but at low risk of kidney cancer." (PMID 35785036, 2022). "Moreover, NOD2-deficiency has been shown to cause dysbiosis in mice, including a higher abundance of Rikenella, which induced transmissible colitis and colorectal cancer." (PMID 28713378, 2017). "In conclusion, it appears that independently both the TNFα-1031T/T and the NOD2 3020insC polymorphisms may act as low risk modifiers of colorectal cancer risk." (PMID 18433468, 2008). "Recently, NOD2/CARD15 was found to increase the risk for colorectal cancer (CRC)." (PMID 17389035, 2007). "To assess the potential prognostic value of NOD2 in colorectal cancer, we assessed the transcriptome of 402 colorectal tumors from the TCGA-COAD cancer project that was available in the data repository of the Cancer Genome Atlas." (PMID 37876927, 2023). "The 3020insC variant of NOD2/CARD15 also predisposes cells to many types of common cancers, mainly solid tumors—for example, ovarian cancer, breast cancer, and colorectal cancer." (PMID 32596371, 2020). "Nod2-dependent protection from colorectal cancer was dependent on the inhibition of TLR-mediated activation of NF-κB and MAPK signaling." (PMID 33239685, 2020). "Frequency of the combined genotypes (TNFα-1031T/C & NOD2 3020insC) and changes in the OR with increasing age of diagnosis in consecutively collected colorectal cancer patients." (PMID 18433468, 2008).